ENSG00000280968
Gene: MicroRNA gene on chromosome 22 (29,333,158 to 29,333,267, reverse strand). Ensembl gene ENSG00000280968.
Gene Ontology:
Biological process: RNA processing
Cellular component: nucleolus